RAB3C (RAB3C, member RAS oncogene family)
Description:
The small GTPases Rab are key regulators of intracellular membrane trafficking, from the formation of transport vesicles to their fusion with membranes. Rabs cycle between an inactive GDP-bound form and an active GTP-bound form that is able to recruit to membranes different sets of downstream effectors directly responsible for vesicle formation, movement, tethering and fusion.
Tractability: Small molecule: a structure with a bound ligand is known. Antibody: UniProt places it where antibodies can reach, with high confidence; its Gene Ontology location is reachable by antibodies, with medium confidence. PROTAC: ubiquitination databases record sites on it; its protein half-life has been measured.
Gene: Protein-coding gene on chromosome 5 (58,582,221 to 58,859,394, forward strand). Ensembl gene ENSG00000152932.
Subcellular location: Cell membrane
Subcellular location (Human Protein Atlas): Cytosol
Pathways (Reactome):
Metabolism of proteins: RAB geranylgeranylation
Gene Ontology:
Molecular function: GTPase activity; myosin V binding; protein binding; G protein activity; GTP binding; GTP-dependent protein binding
Biological process: antigen processing and presentation; exocytosis
Cellular component: perinuclear region of cytoplasm; vesicle; endosome; plasma membrane; synaptic vesicle
Genetic constraint (gnomAD): Loss-of-function variants: 8 observed, 13.51 expected, observed/expected ratio (o/e) 0.59, 90% interval 0.35 to 1.07. The upper end of that interval is the gene's LOEUF score, 1.07, which puts it in group 4 of 6, group 1 being the genes least tolerant of losing a copy. Missense variants: 189 observed, 221.22 expected, observed/expected ratio (o/e) 0.85, 90% interval 0.76 to 0.96. Synonymous variants: 71 observed, 80.12 expected, observed/expected ratio (o/e) 0.89, 90% interval 0.73 to 1.08.
Homologues: Orthologues: chimpanzee RAB3C (100% identical), macaque RAB3C (98% identical), guinea pig RAB3C (97% identical), mouse Rab3c (97% identical), rat Rab3c (97% identical), dog RAB3C (96% identical), pig RAB3C (95% identical), rabbit RAB3C (95% identical), tropical clawed frog rab3c (92% identical), zebrafish rab3c (78% identical). Paralogues in human: RAB3A (81% identical), RAB3B (78% identical), RAB3D (71% identical), RAB8A (45% identical), RAB10 (43% identical), RAB8B (43% identical), RAB13 (42% identical), RAB1A (41% identical), RAB12 (40% identical), RAB1B (39% identical), RAB35 (38% identical), RAB27A (38% identical), and 56 more.
Diseases named in the same sentence as RAB3C in open-access papers:
RAB3C is named in the same sentence as 11 diseases in open-access papers, as found by Europe PMC text mining. Sharing a sentence is not in itself a finding about the gene and the disease. The quoted sentences say what the papers report.
colorectal cancer (5 papers, 2017 to 2023). A primary or metastatic malignant neoplasm that affects the colon or rectum. "Other RAB family proteins such as RAB3C have been reported to regulate the secretion of IL6 to promote colorectal cancer metastasis, the underlying mechanism of which still needs to be elucidated." (PMID 33072555, 2020). "Our study revealed that RAB3C overexpression promotes tumor metastasis and is associated with poor prognosis in colorectal cancer, through modulating the ability of cancer cells to release IL-6 through exocytosis and activate the JAK2-STAT3 signaling pathway." (PMID 28784136, 2017). "This study demonstrated that RAB3C overexpression is associated with tumor metastasis and poor prognosis in colorectal cancer, through modulating exocytosis of IL-6 in cancer cells, thus leading to activation of the IL6-JAK2-STAT3 pathway." (PMID 28784136, 2017). "Collectively, RAB3C upregulation facilitates colorectal cancer metastasis by promoting IL-6 secretion and recruiting members of the STAT3-related pathway." (PMID 28784136, 2017). "After identifying RAB3C in all 8 exocytic RABs, we further analyzed the prognostic impact of RAB3C in colorectal cancer patients." (PMID 28784136, 2017). "In this study, the high expression of RAB3C in colorectal cancer tissue compared with that in normal colonic mucosal tissue provided strong evidence allowing us to determine its value as a prognostic indicator." (PMID 28784136, 2017). "In conclusion, increased RAB3C expression is correlated with poor prognosis and distant metastasis in colorectal cancer patients and regulates exocytosis and IL-6 secretion." (PMID 28784136, 2017). "Our immunohistochemistry analysis results showed that high RAB3C expression was significantly correlated with poor prognosis and more frequent distant metastasis in clinical colorectal cancer patients." (PMID 28784136, 2017). "Significant RAB3C overexpression was identified in colorectal cancer tissue compared with normal colonic mucosa and the other 7 exocytic RABs." (PMID 28784136, 2017). "Of all the 215 colorectal cancer patients, high RAB3C expression level defined by moderate to strong cytoplasmic RAB3C IHC staining was observed in 125 (58.1%) cases, and low RAB3C expression level defined by negative or weak cytoplasmic RAB3C IHC staining was observed in 90 (41.9%) cases." (PMID 28784136, 2017). "The metastasis-promoting ability of RAB3C in colorectal cancer in the present study underscored the importance of conducting more research to elucidate whether other RAB3 isoforms and other exocytic RABs also participate in and coordinately regulate exocytosis, thereby leading to tumor metastasis." (PMID 28784136, 2017).
colon cancer (4 papers, 2017 to 2023). "Here we demonstrate that RAB3C dominates the drug resistance and exocytosis in colon cancer, and that dystrophin also plays a role." (PMID 36652260, 2023). "The cannabinoid receptor type 2 (CB2) agonist was also considered to be an RAB3C‐induced phenotypic inhibitor in colon cancer cells." (PMID 36652260, 2023). "According to the results, there were consistent trends across the multiple chemodrugs; however, the regorafenib sensitivity was inversely correlated with the RAB3C‐expression level in colon cancer." (PMID 36652260, 2023). "We further established RAB3C‐overexpression cell models in several low‐endogenous‐expression colon cancer cells, including SW480 and SW48." (PMID 36652260, 2023). "To identify potential strategies for further application in the clinic, we compared the IC50 of several PIK3CA inhibitors and the endogenous levels of RAB3C and dystrophin in the colon cancer cell panel." (PMID 36652260, 2023). "On the other hand, IL-6 can induce STAT3 phosphorylation in colon cancer cells with overexpressed RAB3C, which promotes the migration of colon cancer cells." (PMID 33718596, 2021). "RAB3C was reported to promote colon cancer metastasis by modulating the IL-6-STAT3 pathway, forced expression of RAB3C led to upregulation of other secretory RABs including RAB2642." (PMID 31511502, 2019). "RAB3C overexpression was also confirmed to increase the migration and invasion ability of colon cancer cells and the number of metastatic nodules in animal models." (PMID 28784136, 2017). "To further confirm the role of the RAB3C-IL-6 axis in colon cancer metastasis, we analyzed the canonical pathway of IL-6 by examining previous data." (PMID 28784136, 2017). "On the basis of the evidence presented above, we propose that RAB3C overexpression in colon cancer cells induces IL-6 exocytosis, thereby triggering JAK2 activation and STAT3 phosphorylation and inducing cancer cell metastasis." (PMID 28784136, 2017). "The results showed that decreased RAB3C expression downregulated the migration/invasion ability in colon cancer cells." (PMID 28784136, 2017). "We detected the endogeous RAB3C protein levels in colon cancer cell panel and observed higher RAB3C expressions in more malignant cell lines (lane 4–8)." (PMID 28784136, 2017). "We observed that IL-6 knockdown decreased the RAB3C-enhanced migration/invasion ability of colon cancer cells, thus indicating a critical role of the RAB3C-IL-6 axis in promoting the metastatic potential of colon cancer cells." (PMID 28784136, 2017). "Increases in migration and invasion ability in vitro and the metastasis-promoting ability in vivo were found after RAB3C overexpression in colon cancer cells." (PMID 28784136, 2017). "We observed that the IL-6 production was positively correlated with the endogenous RAB3C protein level in a panel of colon cancer cell lines." (PMID 28784136, 2017). "In transwell migration and invasion assays, increased cell migration and invasion ability was observed in colon cancer cell lines after RAB3C overexpression." (PMID 28784136, 2017). "Thus, detecting the RAB3C/dystrophin expression in colon cancer can reflect the patient's prognosis, as well as his/her response to targeted therapy applications." (PMID 36652260, 2023). "The authors found that RAB3C overexpression induces dystrophin expression to promote vesicle formation and packaging for increased exocytosis, is related to drug resistance and is correlated with PIK3CA/KRAS mutation status in colon cancer." (PMID 36652260, 2023). "The molecular mechanism of RAB3C in inducing colon cancer cell metastasis was determined." (PMID 28784136, 2017). "Therefore, we overexpressed RAB3C in less malignant colon cancer cell lines (CX-1, SW48, and SW480) to investigate the influence of RAB3C ectopic expressions on cancer cell migration and invasion ability." (PMID 28784136, 2017).
colon cancer (continued). "Furthermore, our experimental results showed an increase in the migration and invasion ability of RAB3C-overexpressing colon cancer cells and increased metastatic nodules in a mouse metastasis model." (PMID 28784136, 2017). "In two colon cancer cell lines, we observed upregulation of other exocytic RABs including RAB3B, RAB26, and RAB27A as a result of RAB3C overexpression." (PMID 28784136, 2017).
breast carcinoma (2 papers, 2019 to 2023). "Elevated expression of RAB3C promotes in vivo migration, invasion, and metastasis of colorectal cancer while RAB3D induced breast cancer cell invasion by activating Akt/GSK-3β/Snail pathway." (PMID 36769293, 2023). "Further, endocytic proteins of the RAB subfamily such as RAB3C and RAB3D control invasion and metastasis of colorectal and breast cancer, respectively." (PMID 36769293, 2023).
cervical cancer (2 papers, 2019 to 2023). A primary or metastatic malignant neoplasm involving the cervix. "On the other hand, high SULTIEI, RAB3C, CXCR3, PROX2, and KRT42P expression was associated with a better prognosis in cervical cancer." (PMID 37350944, 2023). "The results showed that high expression of MYH1, MYH4, FGG, and DEPP1 was associated with shorter overall survival of patients with cervical cancer; high expression of SULT1E1, RAB3C, CXCR3, and PROX2 was associated with longer overall survival of patients with cervical cancer." (PMID 37350944, 2023). "High expression of MYH1, MYH4, FGG, DEPP1, and ZBTB16 was associated with shorter overall survival of patients with cervical cancer; high expression of SULT1E1, RAB3C, CXCR3, and PROX2 was associated with longer overall survival of patients with cervical cancer." (PMID 37350944, 2023). "Moreover, we identified four cervical cancer-specific methylation markers, cg07211381 (RAB3C), cg12205729 (GABRA2), cg20708961 (ZNF257), and cg26490054 (SLC5A8), with 96.2% sensitivity and 95.2% specificity by using the tenfold cross-validation of TCGA data." (PMID 31871774, 2019). "We identified four cervical cancer-specific methylation markers, including cg07211381 (RAB3C), cg12205729 (GABRA2), cg20708961 (ZNF257), and cg26490054 (SLC5A8), and the significantly decreased expression of GABRA2, ZNF257, and SLC5A8 in CSCC was further confirmed in human CSCC tissues by IHC." (PMID 31871774, 2019).
chordoma (1 paper, 2025). Chordomas are rare malignant tumors arising from embryonic remnants of the notochord in axial skeleton. "To evaluate the roles of other RAB3 members in the chordoma stemness and tumorigenic functions, we found that RAB3A, RAB3C, and RAB3D regulated the proliferation of CH22 cells, whereas they did not control the expressions of stemness markers, such as TBXT, NANOG, OCT4 and SOX2." (PMID 40135815, 2025).
Hypertension (1 paper, 2022). The presence of chronic increased pressure in the systemic arterial system. "Differentially expressed PNMT, MPZ, RAB3C, and CD36 can be potential targets for AMH, providing a theoretical basis for mechanistic exploration of AMH along with hypertension." (PMID 36583008, 2022). "Of note, PNMT, MPZ, RAB3C, and CD36 are found to differentially expressed and can be potential targets for AMH, providing a theoretical basis for mechanistic exploration of AMH along with hypertension." (PMID 36583008, 2022).
teratozoospermia (1 paper, 2022). "This study demonstrated the localization of RAB3C on male germ cells and the association between RAB3C and SEPT14 mutation-induced teratozoospermia." (PMID 36295569, 2022).
cancer (8 papers, 2017 to 2025). A tumor composed of atypical neoplastic, often pleomorphic cells that invade other tissues. "However, the function of RAB3C is relatively unclear, and an association between RAB3C and cancer has yet to be determined." (PMID 28784136, 2017). "We have established RAB3C‐based transcriptomic datasets and provided evidence that RAB3C promotes cancer metastasis through the IL‐6/STAT3 axis to affect patient survival." (PMID 36652260, 2023). "According to these data, the RAB3C/dystrophin protein has prognostic value in cancer progression, and it can be used as a therapeutic target for improving the survival rates of patients." (PMID 36652260, 2023). "And some identified 3′-UTR piSNV-affected genes, such as SLC6A11, NUDCD2, CTNNA3, RAB3C, and AJAP1, are well-studied cancer/disease related genes with a high deleterious mutation rate." (PMID 35654793, 2022). "In the present study, we found that IL-6 secretion is the major mechanism by which RAB3C induces cancer metastasis." (PMID 28784136, 2017). "An IHC analysis was performed to compare the RAB3C protein expression levels in both normal and cancer tissues." (PMID 28784136, 2017). "Notably, at least two of the FOXA2 transcriptional targets identified by our analysis (ANK2 and RAB3C) are known to promote cancer progression and metastasis." (PMID 33793068, 2021). "Our research is the first study focused on the role and the function of RAB3C in cancer." (PMID 28784136, 2017). "To determine whether the RAB3C and dystrophin are related to the clinicopathological parameters of cancer patients, we performed the IHC staining of dystrophin and RAB3C on the colorectal tissue arrays to assess whether their expressions can be considered predictors of a poor prognosis in CRC." (PMID 36652260, 2023).
tumor (4 papers, 2017 to 2023). "In this dataset, among all 8 of the exocytic RABs, we also observed the strongest association between RAB3C and tumor grade (P = 0.002)." (PMID 28784136, 2017). "According to our data, the RAB3C and dystrophin demonstrated coordinated expression, and the tumor tissues exhibited stronger staining than the adjacent normal tissues." (PMID 36652260, 2023). "According to our results, RAB3C was substantially more expressed in the tumor cells than in normal primary cells." (PMID 36652260, 2023). "Together, these results indicated that the RAB3C protein plays a critical role in tumor progression, invasion, and metastasis through IL-6 exocytosis." (PMID 28784136, 2017). "RAB3C immunoreactivity was significantly more intense and diffuse in tumor tissue compared with normal tissue (P < 0.001)." (PMID 28784136, 2017). "High RAB3C expression was positively correlated with higher M stage (P < 0.001), higher pathological stage (P = 0.044), and tumor recurrence (P = 0.006)." (PMID 28784136, 2017). "Similarly, compared with normal adjacent tissues, we also observed the increased expression of RAB3C in tumor tissues." (PMID 36652260, 2023). "The strong effects of RAB3C expression on disease-free survival and tumor recurrence in the present study may be attributed to treatment resistance modulated by RAB3C." (PMID 28784136, 2017). "Another interesting finding was that tumor cells with unusual mitotic figures were observed in tumor nodules of RAB3C-overexpressing cells, whereas no unusual mitotic figures were seen in vector control tumor cells." (PMID 28784136, 2017).
RAB3C also shares sentences with these, for which no sentence is quoted: infection (1 paper); Insulin resistance (1).